PIGT (phosphatidylinositol glycan anchor biosynthesis class T)
Description:
Component of the glycosylphosphatidylinositol-anchor (GPI-anchor) transamidase (GPI-T) complex that catalyzes the formation of the linkage between a proprotein and a GPI-anchor and participates in GPI anchored protein biosynthesis. May play a crucial role in GPI-T complex assembly in the luminal layer. Binds GPI-anchor.
Synonyms: CGI-06; PIG-T; MCAHS3; NDAP; PNH2
Tractability: Small molecule: a structure with a bound ligand is known. Antibody: UniProt predicts a signal peptide or a membrane-spanning region. PROTAC: ubiquitination databases record sites on it; its protein half-life has been measured.
Gene: Protein-coding gene on chromosome 20 (45,416,084 to 45,456,934, forward strand). Ensembl gene ENSG00000124155.
Subcellular location: Endoplasmic reticulum membrane
Pathways (Reactome):
Metabolism of proteins: Attachment of GPI anchor to uPAR
Gene Ontology:
Molecular function: GPI anchor binding; protein binding
Biological process: attachment of GPI anchor to protein; GPI anchored protein biosynthesis; GPI anchor biosynthetic process
Cellular component: GPI-anchor transamidase complex; membrane; endoplasmic reticulum membrane; cytoplasm; cytoplasmic vesicle
Genetic constraint (gnomAD): Loss-of-function variants: 55 observed, 63.51 expected, observed/expected ratio (o/e) 0.87, 90% interval 0.7 to 1.08. The upper end of that interval is the gene's LOEUF score, 1.08, which puts it in group 4 of 6, group 1 being the genes least tolerant of losing a copy. Missense variants: 711 observed, 742.37 expected, observed/expected ratio (o/e) 0.96, 90% interval 0.9 to 1.02. Synonymous variants: 352 observed, 321.26 expected, observed/expected ratio (o/e) 1.1, 90% interval 1 to 1.2.
Gene-disease validity (ClinGen):
ClinGen rates the evidence that PIGT causes each of these diseases.
multiple congenital anomalies-hypotonia-seizures syndrome 3 (autosomal recessive): Definitive.
Homologues: Orthologues: chimpanzee PIGT (99% identical), macaque PIGT (99% identical), guinea pig PIGT (94% identical), rat Pigt (94% identical), mouse Pigt (94% identical), dog PIGT (93% identical), pig PIGT (93% identical), tropical clawed frog pigt (71% identical), zebrafish pigt (67% identical), Drosophila melanogaster PIG-T (37% identical), Caenorhabditis elegans pigt-1 (24% identical).
Diseases named in the same sentence as PIGT in open-access papers:
PIGT is named in the same sentence as 32 diseases in open-access papers, as found by Europe PMC text mining. Sharing a sentence is not in itself a finding about the gene and the disease. The quoted sentences say what the papers report.
breast carcinoma (5 papers, 2014 to 2024). "Previous studies have demonstrated that other PIG class members, such as PIGU and PIGT, are oncogenes in either human bladder cancer or breast cancer, respectively." (PMID 24483146, 2014). "PIGT and its gene products have been hypothesized to play a role in growth of breast cancer via paxillin phosphorylation." (PMID 32396573, 2020).
bladder cancer (3 papers, 2014 to 2025). "GEPIA indicated that expression of PIGT was increased in tumor compared with normal tissue and high levels of PIGT were associated with shorter survival times of patients with bladder cancer in TCGA dataset." (PMID 38169393, 2024). "Together, the data indicate that PIGT knockdown inhibits cell proliferation, oxidative phosphorylation and glycolysis in bladder cancer cells." (PMID 38169393, 2024). "To determine the relevance of the regulation of PIGT, WTAP and GLUT1 in patients, we performed IHC staining of PIGT, WTAP, and GLUT1 on the bladder cancer tissue microarrays and tumor tissues were separated into PIGT-high/low-group." (PMID 38169393, 2024). "We have demonstrated that silencing PIGT suppresses cell growth, oxidative phosphorylation, and glycolysis in bladder cancer cells, whereas overexpressing PIGT promotes cell proliferation, oxidative phosphorylation, and glycolysis via activating GLUT1." (PMID 38169393, 2024). "The results indicate a novel role of WTAP in bladder cancer, demonstrating that WTAP increases the m6A modification of PIGT through IGF2BP2 to contribute to bladder cancer progression." (PMID 38169393, 2024). "In the current study, we revealed a new role of PIGT in bladder cancer, showing that PIGT regulates cell proliferation, oxidative phosphorylation, and glycolysis in bladder cancer cells." (PMID 38169393, 2024). "Then, the expression of PIGT in bladder cancer tissue microarrays was detected by IHC." (PMID 38169393, 2024). "PIGT was silenced or overexpressed to study its role in regulating bladder cancer." (PMID 38169393, 2024). "Given the increased mRNA and protein expression of PIGT in bladder cancer tissues and cell lines, we further investigated whether PIGT is regulated by m6A modification in bladder cancer." (PMID 38169393, 2024). "Therefore, we aim to study the role of PIGT and GLUT1 in bladder cancer and its underlying mechanisms." (PMID 38169393, 2024). "Compare to PIGU, the role of PIGT in cancer, especially in bladder cancer, is poorly understood." (PMID 38169393, 2024). "However, how PIGT is regulated and what is the function of PIGT in bladder cancer remains to be elucidated." (PMID 38169393, 2024). "Data indicated that PIGT was remarkably up-regulated in bladder cancer." (PMID 38169393, 2024). "Furthermore, the expression of PIGT was notably correlated with four of the clinicopathologic characteristics, pathological stage, grade, lymph node metastasis and vascular invasion, in the patients with bladder cancer." (PMID 38169393, 2024). "In bladder cancer, WTAP promotes m6A modification within the 3’ UTR of PIGT mRNA and interacts with IGF2BP2 to enhance transcript stability, thereby increasing PIGT expression." (PMID 40859309, 2025). "WTAP mediates PIGT m6A modification to increase the stability of PIGT via the IGF2BP2, which enhances cell proliferation, glycolysis, and metastasis in bladder cancer by modulating GLUT1 glycosylation and membrane trafficking." (PMID 38169393, 2024). "PIGT’s counterpart, PIGU, has been shown to be increased in bladder cancer, and more importantly, study showed that overexpressing PIGU malignantly transformed NIH3T3 cells." (PMID 38169393, 2024). "This study demonstrated a novel function of PIGT, showing that PIGT enhances cell growth, glycolysis, and metastasis in bladder cancer by modulating GLUT1 glycosylation and membrane trafficking and that WTAP increases m6A modification of PIGT through m6A reader, IGF2BP2." (PMID 38169393, 2024). "Moreover, correlation analysis demonstrated that PIGT expression was positively correlated with WTAP and GLUT1 expression in bladder cancer tissues." (PMID 38169393, 2024).
paroxysmal nocturnal hemoglobinuria (3 papers, 2021 to 2025). Paroxysmal nocturnal hemoglobinuria (PNH) is an acquired clonal hematopoietic stem cell disorder characterized by corpuscular hemolytic anemia, bone marrow failure and frequent thrombotic events. "In mammals, free GPIs have been detected in several tissues and pathogenic conditions of paroxysmal nocturnal hemoglobinuria caused by PIGT mutation and rare blood group phenotypes." (PMID 41373744, 2025). "In addition, somatic PIGT mutations in hematopoietic stem cells cause a type of paroxysmal nocturnal hemoglobinuria (PNH) that has autoinflammatory features such as aseptic meningitis." (PMID 34576938, 2021).
developmental delay (2 papers, 2021 to 2024). "We described a PIGT mutation in an Indian girl with global developmental delay, infantile-onset seizures, hypotonia, and facial dysmorphism." (PMID 34084664, 2021).
gastric cancer (2 papers, 2019 to 2021). A primary or metastatic malignant neoplasm involving the stomach. "In breast, bladder, and gastric cancer, the high expression of other GPI-anchor biosynthesis glycogenes, such as PIGU, PIGT, and PIGX, is associated with oncogenesis, poor prognosis, and tumorigenesis." (PMID 34540372, 2021).
hypophosphatasia (2 papers, 2020 to 2025). Hypophosphatasia (HPP) is a rare heritable metabolic disorder characterized by defective mineralization of bone and/or teeth in the presence of reduced activity of unfractionated serum alkaline phosphatase (ALP). "In contrast, hypophosphatasia was a particularly distinctive feature in patients with PIGT mutations (7/13 patients with available data)." (PMID 32220244, 2020).
multiple congenital anomalies-hypotonia-seizures syndrome 3 (2 papers, 2024 to 2025). "Biallelic pathogenic variants in PIGT are associated with Multiple Congenital Anomalies-Hypotonia Seizures Syndrome 3 (MCAHS3), a rare neonatal hypotonia syndrome characterized by dysmorphic features and seizures." (PMID 40141433, 2025). "Biallelic pathogenic variants in PIGT are associated with Multiple Congenital Anomalies-Hypotonia Seizures Syndrome 3 (MCAHS3, OMIM 615398)." (PMID 40141433, 2025). "Multiple congenital anomalies-hypotonia-seizures syndrome 3 (MCAHS3) results from mutations in the phosphatidylinositol glycan biosynthesis class T (PIGT) gene leading to defects in glycosylphosphatidylinositol transamidase complex (GPI-TA) synthesis." (PMID 38903302, 2024).
developmental and epileptic encephalopathy (1 paper, 2021). An epilepsy associated with developmental impairment that may be due to either the underlying etiology or the superimposed epileptic activity, or both. "Our study gives evidence to the claim that Asn527Ser- and Val528Met-related PIGT deficiency is associated with a mild to moderate “developmental and epileptic encephalopathy (DEE)”, as compared to PIGT-related DEE caused by other pathogenic variants." (PMID 34046058, 2021).
glioma (1 paper, 2025). A benign or malignant brain and spinal cord tumor that arises from glial cells (astrocytes, oligodendrocytes, ependymal cells). "Furthermore, BMP2, NCF1, HSPB1, PIGT, PTX3, CCNA2, and CCNB2 exhibited increased expression, while DES displayed decreased expression in glioma tissues." (PMID 40656950, 2025).
glycosylphosphatidylinositol deficiency (1 paper, 2025). "The latest study also found that patients with inherited glycosylphosphatidylinositol deficiency (IGD) disorders carrying PIGT mutations mostly exhibit low ALP levels (n = 4), while others have normal levels (n = 3)." (PMID 40141433, 2025).
Hypercalciuria (1 paper, 2018). "None of the patients with PIGT related MCAHS3 was reported to have a nail, skin or hair anomaly while most of the other genes did, on the contrary, only patients of PIGT related MCAHS3 was reported to have hypercalciuria." (PMID 29868109, 2018).
intellectual disability syndrome (1 paper, 2022). "Homozygous mutations in the human PIGT gene leading to glycosylphosphatidylinositol (GPI) anchor deficiency was reported to cause a novel intellectual disability syndrome." (PMID 36614124, 2022).
melanoma (1 paper, 2022). A malignant, usually aggressive tumor composed of atypical, neoplastic melanocytes. "The most significant differences in melanoma are NOMO1, PIGT, VKORC1, PDIA5 and DDX11, and the most significant differences in uterine cancer are CTU2, EMC8, TUBG1, CLPP and LONP1." (PMID 34951103, 2022).
microcephaly (1 paper, 2023). A congenital or acquired developmental disorder in which the circumference of the head is smaller than normal for the person's age and sex. "Microcephaly has its highest prevalence in patients with PIGK and PIGS involvement, while PIGT mutated can be macrocephalic." (PMID 37510348, 2023).
myoclonic atonic epilepsy (1 paper, 2021). "Our data show that PIGT is a new candidate gene for myoclonic atonic epilepsy." (PMID 34046058, 2021).
respiratory infection (1 paper, 2018). "Another noteworthy point is, no PIGT mutant except our proband has been reported with airway softening, leading to expectoration difficulty, which may aggravate the recurrent respiratory infection." (PMID 29868109, 2018).
Sleep apnea (1 paper, 2025). An intermittent cessation of airflow at the mouth and nose during sleep is known as sleep apnea. "Though the gene with the highest loading on LV3, SRSF4, has not been previously associated with sleep apnea, the second and third highest loading genes, PIGT and PRPS1, were included in the HPO sleep apnea gene set." (PMID 40662804, 2025).
cancer (5 papers, 2018 to 2024). A tumor composed of atypical neoplastic, often pleomorphic cells that invade other tissues. "Further, overexpression of PIGT protein has also been observed in several other cancer types." (PMID 32396573, 2020). "PIGT, PIGU, GPAA1, and PIGS are overexpressed in many cancers, whereas PIGK is downregulated." (PMID 34193731, 2021).
tumor (3 papers, 2024 to 2026). "More importantly, in animal studies, GLUT1 silencing inhibited PIGT overexpression-induced tumor metastasis." (PMID 38169393, 2024). "GLUT1 silencing dramatically inhibited PIGT overexpression-induced decreased survival rates of tumor-bearing mice." (PMID 38169393, 2024). "Overexpressing PIGT promoted cell proliferation, oxidative phosphorylation, glycolysis in vitro and tumor metastasis in vivo by activating glucose transporter 1 (GLUT1)." (PMID 38169393, 2024). "We found that PIGT knockdown also significantly inhibited tumor lung metastasis, and increased survival rates of tumor-bearing mice." (PMID 38169393, 2024). "Notably, the upregulation of several of these genes, particularly NCF1, HSPB1, PIGT, and PTX3, was associated with poor prognosis, supporting the idea that these genes play a pivotal role in tumor progression and patient survival." (PMID 40656950, 2025).
infection (1 paper, 2025). The state of being infected such as from the introduction of a foreign agent such as serum, vaccine, antigenic substance or organism. "We also found that PIGT-, PIGH- or GPAA1-KO cells did not support Echo7 infection." (PMID 41252368, 2025).
PIGT also shares sentences with these, for which no sentence is quoted: epilepsy (3 papers); genetic diseases (2); absence seizures (1); Angelman syndrome (1); atrial septal defect (1); Cerebral ischemia (1); generalized tonic-clonic seizures (1); lymph node metastasis (1); Multiple Congenital Anomalies (1); myoclonic seizures (1); Patent ductus arteriosus (1); uterine cancer (1).